WBP1LP8 (WBP1L pseudogene 8)
Gene: Processed pseudogene on chromosome 6 (170,651,012 to 170,651,338, reverse strand). Ensembl gene ENSG00000273640.
Diseases named in the same sentence as WBP1LP8 in open-access papers:
WBP1LP8 is named in the same sentence as 1 disease in open-access papers, as found by Europe PMC text mining. Sharing a sentence is not in itself a finding about the gene and the disease. The quoted sentences say what the papers report.
tumor (1 paper, 2022). "Five genes at 6q27 exhibiting large genomic changes (PSMB1, PDCD2, TBP, OR4F7P and WBP1LP8) were found in HCI-010 as the region transitioned from amplified in the human tumor to deleted in the early passage of the PDX and PDxO." (PMID 35221336, 2022).